ZNF581 (zinc finger protein 581)
Description:
May be involved in transcriptional regulation.
Synonyms: HSPC189; FLJ22550
Tractability: PROTAC: ubiquitination databases record sites on it.
Gene: Protein-coding gene on chromosome 19 (55,635,018 to 55,645,626, forward strand). Ensembl gene ENSG00000171425.
Subcellular location: Nucleus
Subcellular location (Human Protein Atlas): Nucleoplasm; Vesicles; Cytosol
Gene Ontology:
Molecular function: protein binding; DNA-binding transcription factor activity; RNA polymerase II cis-regulatory region sequence-specific DNA binding
Biological process: regulation of transcription by RNA polymerase II
Cellular component: nucleus
Genetic constraint (gnomAD): Loss-of-function variants: 2 observed, 2.89 expected, observed/expected ratio (o/e) 0.69, 90% interval 0.27 to 1.75. That is too few expected variants to judge how well the gene tolerates losing a copy. Missense variants: 273 observed, 270.74 expected, observed/expected ratio (o/e) 1.01, 90% interval 0.91 to 1.12. Synonymous variants: 105 observed, 105.58 expected, observed/expected ratio (o/e) 0.99, 90% interval 0.85 to 1.17.
Homologues: Orthologues: chimpanzee ZNF581 (100% identical), macaque ZNF581 (99% identical), dog ZNF581 (89% identical), pig ZNF581 (88% identical). Paralogues in human: ZNF524 (48% identical), ZNF580 (46% identical), FEZF1 (28% identical), FEZF2 (26% identical), ZBTB49 (26% identical), BCL6B (25% identical), BCL6 (24% identical), ZBTB7B (23% identical), ZNF683 (22% identical), GFI1 (21% identical), GFI1B (21% identical), PRDM13 (21% identical), and 16 more.
Diseases named in the same sentence as ZNF581 in open-access papers:
ZNF581 is named in the same sentence as 3 diseases in open-access papers, as found by Europe PMC text mining. Sharing a sentence is not in itself a finding about the gene and the disease. The quoted sentences say what the papers report.
cancer (1 paper, 2021). A tumor composed of atypical neoplastic, often pleomorphic cells that invade other tissues. "Regarding the mechanisms of DYRK1B on cancer progression, silencing DYRK1B consistently reduced two rare genes, CCDC97 and ZNF581, the physiological functions of which have not been previously reported." (PMID 34830933, 2021).
tumor (1 paper, 2021). "CCDC97 and ZNF581 were positively correlated with DYRK1B expression and might be involved in DYRK1B-mediated tumor malignancy in TNBC patients, providing DYRK1B as a potential theranostic target for TNBC." (PMID 34830933, 2021).
ZNF581 also shares sentences with these, for which no sentence is quoted: Obesity (1 paper).